KLF4 (KLF transcription factor 4)
Diseases named in the same sentence as KLF4 in open-access papers (continued):
Sharing a sentence is not in itself a finding about the gene and the disease.
keloid (1 paper, 2025). An irregularly shaped, elevated mark on the skin caused by deposits of excessive amounts of collagen during wound healing. "Conversely, the scatter plot for KLF4 shows that all five lines have slopes <0, indicating that KLF4 is a low-risk gene that reduces the risk of keloid development." (PMID 40487928, 2025). "KLF4 was significantly associated with keloids with an IVW OR of 0.492 (95% CI: 0.290–0.835, P = .009), indicating a causal link." (PMID 40487928, 2025). "Conversely, for KLF4, the beta coefficient was negative, and the OR was <1, indicating that increased expression of KLF4 reduces the risk of keloid development." (PMID 40487928, 2025). "Conversely, high expression of KLF4 is negatively correlated with keloid risk, suggesting that KLF4 serves as a protective factor." (PMID 40487928, 2025). "In contrast, the forest plot for KLF4 demonstrates that the combined effect sizes of its associated SNPs are all <0, highlighting its function as a protective gene against keloid formation." (PMID 40487928, 2025). "Specifically, CCND2 is recognized as a risk factor for keloid, while KLF4 functions as a protective factor against keloid formation." (PMID 40487928, 2025). "Bioinformatics and Mendelian randomization analyses identified two intersecting genes, CCND2 and KLF4, as core genes associated with keloid." (PMID 40487928, 2025). "Our analysis confirmed that KLF4 exhibited significant differences in the validation cohort, further supporting its relevance in keloid pathogenesis." (PMID 40487928, 2025). "Validation experiments using the combined dataset from GSE7890 and GSE145725 confirmed that KLF4 exhibited significant differences in the validation cohort, further reinforcing its potential role in keloid pathogenesis." (PMID 40487928, 2025). "In conclusion, KLF4 emerges as a critical regulator of keloid formation through its multifaceted effects on cell growth, fibrosis inhibition, and ECM receptor interactions." (PMID 40487928, 2025). "The MR results for the two core genes (CCND2 and KLF4) in relation to keloid were evaluated for heterogeneity using Cochran’s Q statistic, with additional tests performed using the MR Egger and IVW methods." (PMID 40487928, 2025). "This study not only highlights the pivotal roles of CCND2 and KLF4 in the development of keloids but also provides novel molecular targets and a theoretical foundation for the prevention and treatment of keloids." (PMID 40487928, 2025). "Consequently, CCND2 and KLF4 were identified as core genes in our study, providing valuable insights into the pathogenesis of keloids and highlighting potential targets for therapeutic intervention." (PMID 40487928, 2025). "In contrast, KLF4 demonstrated a negative association, indicating a protective effect against keloid development (IVW OR: 0.492; 95% CI: 0.290–0.835, P = .009)." (PMID 40487928, 2025). "Further research into the precise mechanisms by which KLF4 influences keloid development may pave the way for novel therapeutic strategies to address this debilitating condition." (PMID 40487928, 2025).
kidney cancer (1 paper, 2015). Primary or metastatic malignant neoplasm involving the kidney. "We first compared the expression of the OCT4, NANOG, LIN28, and KLF4 stem cell transcription factors between the parental kidney cancer cell lines and their sphere derivatives." (PMID 25011053, 2015).
kidney injury (1 paper, 2020). Trauma to the kidney. "Furthermore, consistent with a previous finding in the mouse model with acute kidney injury, overexpression of Klf4 also inhibited adhesion cytokines, including VCAM‐1 and ICAM‐1 (P < .05)." (PMID 31800161, 2020).
leiomyoma (1 paper, 2018). A well-circumscribed benign smooth muscle neoplasm characterized by the presence of spindle cells with cigar-shaped nuclei, interlacing fascicles, and a whorled pattern. "Both cell types expressed NANGO, OCT4, SOX2, and KLF4, tested by RT-PCR and cytofluorometry, with a higher expression in leiomyoma cells." (PMID 29861738, 2018).
liver dysfunction (1 paper, 2021). "In summary, this is the first study describing USP11 as a modulator of KLF4 in liver dysfunction." (PMID 34114341, 2021).
Lymphatic Metastasis (1 paper, 2014). Transfer of a neoplasm from its primary site to lymph nodes or to distant parts of the body by way of the lymphatic system. "When the cancer samples were grouped according to their clinical pathological features, the KLF4 methylation status did not correlate with the histological grade, clinical stage, or lymphatic metastasis age of the patients (P>0.05)." (PMID 24551169, 2014).
MELAS syndrome (1 paper, 2019). MELAS (Mitochondrial myopathy, encephalopathy, lactic acidosis, and stroke) syndrome is a rare progressive multisystemic disorder characterized by encephalomyopathy, lactic acidosis, and stroke-like episodes. "We reprogrammed fibroblasts from a seven year-old boy with MELAS syndrome harboring 95% mtDNA A3243G mutation to iPS cells using retroviral vectors expressing Oct4, Klf4, Sox2, and c-Myc." (PMID 30658448, 2019).
Meningothelial Meningioma (1 paper, 2021). A WHO grade I meningioma characterized by the presence of tumor cells that form lobules. "The proportion of meningothelial meningiomas harboring AKT1, KLF4, SMO, or POLR2A mutations was significantly high." (PMID 33772057, 2021).
microphthalmia (1 paper, 2022). Congenital or developmental anomaly in which the eyeballs are abnormally small. "Considering the role Klf4 has in eye lens maturation, a downregulation of klf4 mRNA expression due to an inhibition of miR-203a likely contributed to microphthalmia in treated fish, which could have implications to visual acuity and foraging behavior in ELS fish." (PMID 35284238, 2022).
monocytic leukemia (1 paper, 2021). "KLF4 shows higher expression in monocytic leukemia compared to other AML subtypes, which comprise M4 and M5 AMLs in the FAB classification system and frequently feature MLL-rearrangements." (PMID 33659038, 2021). "Although KLF4 is known to regulate monocytic development, the function of KLF4 expression in monocytic leukemia has not been thoroughly explored." (PMID 33659038, 2021).
mucinous adenocarcinoma (1 paper, 2016). An invasive adenocarcinoma composed of malignant glandular cells which contain intracytoplasmic mucin. "We found that signet ring cell carcinoma and mucinous adenocarcinoma have the highest total score of MUC2, while KLF4 score is variable in these tumors due to different localization of KLF4 in the tissues." (PMID 27277677, 2016).
multiple endocrine neoplasia type 1 (1 paper, 2020). An autosomal dominant tumor predisposition syndrome caused by pathogenic variants in the MEN1 gene, characterized by an increased risk of tumors of the parathyroid glands, pituitary gland, and foregut neuroendocrine tumors (most commonly pancreatic islet cells). "Additionally, in a neuroendocrine application, cells obtained from the urine of patients with multiple endocrine neoplasia type 1 syndrome (MEN1) were used to generate iPSCs with non-integrated episomal plasmids carrying Oct4, Sox2, Klf4, and miR-302-367 without using c-Myc." (PMID 31760627, 2020).
myeloid malignancies (1 paper, 2020). "Although KLF4 has been regarded as a promising therapeutic target in myeloid malignancies, the precise mechanisms of KLF4-mediated tumor suppression or differentiation have been poorly understood." (PMID 33219287, 2020).
Nephroblastoma (1 paper, 2025). An embryonal neoplasm characterized by the presence of epithelial, mesenchymal, and blastema components. "CircPRMT5 (circRNA derived from Protein Arginine Methyltransferase 5 gene) affects the axis miR-7-5p/KLF4 in the rare pediatric tumor nephroblastoma." (PMID 40863723, 2025). "Specifically, inverse correlations between circ-PRMT5-miR-7-5p and between miR-7-5p-KLF4 have been observed (total of n = 45 Wilms’ tumor samples)." (PMID 40863723, 2025).
optic neuritis (1 paper, 2020). Optic neuritis is inflammation of the optic nerve, the nerve that carries the visual signal from the eye to the brain.The conditionmay cause sudden, reduced vision in the affected eye(s). "More importantly, however, Klf4 gene KO after the onset of optic neuritis also resulted in RGC neuroprotection with additional restoration of their function, thereby improving the visual function outcomes in the EAE model." (PMID 32165410, 2020). "For this reason, in the current study we decided to test whether targeted Klf4 gene deletion after the disease onset could alleviate optic neuritis in EAE-challenged mice." (PMID 32165410, 2020). "This study establishes the efficacy of Klf4 targeted knock-down in EAE even after the onset of disease symptoms, and thus should be further explored as a potential treatment strategy for MS/optic neuritis patients." (PMID 32165410, 2020).
orchitis (1 paper, 2021). Inflammation of one or both testes due to viral or bacterial infections. "On the other hand, Klf2, Klf4, Nfe2l2/Nrf2, Id1, Id2, Rad21, Xrcc1, and Cycs were found to be negatively correlated with androgen synthesis during orchitis." (PMID 35111154, 2021).
Osteopenia (1 paper, 2025). Osteopenia is a term to define bone density that is not normal but also not as low as osteoporosis. "To further analyze the diversity of MSCs in osteopenia and their potential functional differentiation, we conducted a detailed subtype analysis and identified three MSC subtypes with different molecular characteristics and functional states: C1 SIX1+ MSCs, C2 NR4A1+ MSCs, and C3 KLF4+ MSCs." (PMID 41262236, 2025).
osteoporosis (1 paper, 2023). A condition of reduced bone mass, with decreased cortical thickness and a decrease in the number and size of the trabeculae of cancellous bone (but normal chemical composition), resulting in increased fracture incidence. "SOX5 was found to be up regulated in human MSCs isolated from bone marrow samples of postmenopausal osteoporosis patients, and it was recognized as a therapeutic target through regulation of the KLF4 signalling pathway in the treatment of this osteoporosis in females." (PMID 36614288, 2023).
ovarian dysfunction (1 paper, 2023). The inability of the ovaries to function. "Moreover, miR-145 was reported to protect GCs against oxidative stress-induced apoptosis by targeting KLF4 (encoding Kruppel-like factor 4), thereby preventing abnormal follicular atresia and improving the outcomes of ovarian dysfunction." (PMID 37537658, 2023).
pancreatitis (1 paper, 2025). Inflammation of the pancreas. "Klf4 is a known player in injury and inflammation and has been found to be necessary and sufficient for ADM in mouse models of pancreatitis." (PMID 40156071, 2025).
parasitic infections (1 paper, 2025). "Also in parasitic infections, KLF4 has been shown to be involved in macrophage activation." (PMID 40313940, 2025).
periodontitis (1 paper, 2025). An acute or chronic inflammatory process that affects the tissues that surround and support the teeth. "The prominent role of Klf4 underscores the importance of transcriptional regulation in orchestrating the dynamic interplay among inflammation, tissue damage, and repair during periodontitis progression." (PMID 40076622, 2025). "By promoting keratinocyte differentiation and mitigating oxidative stress, Klf4 may aid in preserving gingival health during inflammatory challenges in periodontitis." (PMID 40076622, 2025).
pinguecula (1 paper, 2021). A yellowish thickened lesion on the conjunctiva near the cornea representing a benign degenerative change in the conjunctiva caused by the leakage and deposition of certain blood proteins through the permeable capillaries near the limbus. "KLF5 and KLF7 encode transcription factors that oppose KLF4 activity; their expression did not change in pterygium or pinguecula." (PMID 34769520, 2021).
pituitary tumor (1 paper, 2025). A benign or malignant neoplasm affecting the pituitary gland. "In this study, we found higher protein and/or mRNA levels of DPPA4‐associated stem cell factors (SOX‐2, OCT‐4, KLF‐4, SNAIL‐1, and Nestin) in PAE male pituitaries, suggesting that PAE similarly enhances estrogen‐induced pituitary tumor cell stemness in both sexes." (PMID 41017273, 2025).
polyp (1 paper, 2021). A usually exophytic mass attached to the underlying tissue by a broad base or a thin stalk. "Although the expression of KLF4 detected in tissue with villous and high-grade dysplasia is higher than that of other polyp tissue, it is also highly expressed in normal colonic tissue." (PMID 34452555, 2021).
postmenopausal osteoporosis (1 paper, 2023). Metabolic disorder associated with fractures of the femoral neck, vertebrae, and distal forearm. "For example, in human mesenchymal stem cells, SOX5 contributed to the pathology of postmenopausal osteoporosis (PMOP), and its silencing increased collagen I and decreased KLF4 expression." (PMID 36835058, 2023).
preeclampsia (1 paper, 2026). Preeclampsia is a hypertensive disorder of pregnancy that is characterized by new-onset hypertension with proteinuria presenting after 20 weeks of gestation, and depending on mild or severe forms may initially present with severe headache, visual disturbances, and hyperreflexia. "We now report that inducible deletion of KLF4 in maternal endothelium (KLF4 iECKO) results in gestational hypertension, elevated sFlt1, defective placental vasculature, kidney damage and fetal growth restriction." (PMID 41959392, 2026).
premature aging syndrome (1 paper, 2019). Changes in the organism associated with senescence, occurring at an accelerated rate. "For example, general, conditional, and transient expression of Oct4, Sox2, Klf4, and c-Myc (OSKM) suppressed cellular and physiological hallmarks of aging and prolonged lifespan in a mouse model of HSPG progeria and premature aging syndrome." (PMID 31310235, 2019).
pressure ulcer (1 paper, 2021). "Basal levels of KLF4 in ob/ob mice are lower than WT mice, and, even with the stimulus of a pressure ulcer, KLF4 expression in ob/ob mice is still reduced in comparison." (PMID 34568499, 2021). "Meanwhile, the current study reveals that APTO-253, a commercialized KLF4 activator, is also able to accelerate the healing of pressure ulcers, making KLF4 upregulation a promising alternative candidate for wound healing applications." (PMID 34568499, 2021). "In this report, we used a pressure ulcer (PU) model in ob/ob mice to show that compromised diabetic wound repair correlates with decreased expression of KLF4 and upregulation of IL-17A." (PMID 34568499, 2021). "The concentrations of IL-1β, IL-6, and TGF-β in blood and wounds were all significantly elevated in response to pressure ulcers while the activation of KLF4 significantly suppressed the expression of these cytokines." (PMID 34568499, 2021). "In this report, using an ob/ob mouse pressure ulcer model, we demonstrated that KLF4-regulated MDSCs promoted diabetic wound healing by suppressing Th17 differentiation and subsequent IL-17A expression." (PMID 34568499, 2021). "Our study revealed a previously unreported function of KLF4-regulated MDSCs in diabetic wound healing and identified APTO-253 as a potential agent to improve the healing of pressure ulcers." (PMID 34568499, 2021).
pterygium (1 paper, 2021). A wedge-shaped fibrovascular lesion arising from the bulbar conjunctiva and extending to the cornea. "This analysis suggests an expansion of cells from the corneal limbal epithelial compartment in pterygium, and identifies KLF4, MYC and POU5F1 and PITX1 as specifically involved." (PMID 34769520, 2021). "We found that genes encoding transcription factors MYC, KLF4, POU5F1 and PITX1 were upregulated in pterygium." (PMID 34769520, 2021). "In the comparison between pinguecula and pterygium subgroups, IPA predicted activation of pathways controlled by MYC, TP63 and KLF4 upstream regulators, which control epithelial cell fate." (PMID 34769520, 2021). "Comparing pinguecula and pterygium, IPA predicted activation of pathways controlled by upstream regulators TP63, MYC and KLF4, transcription factors that control epithelial cell fate." (PMID 34769520, 2021).
relapsing-remitting multiple sclerosis (1 paper, 2018). The most common clinical variant of multiple sclerosis, characterized by recurrent acute exacerbations of neurologic dysfunction followed by partial or complete recovery. "Another group established an hiPSC cell line from fibroblasts isolated from a patient with relapsing-remitting multiple sclerosis (MS) by retroviral transduction using OCT4, SOX2, KLF4 and c-MYC factors (MSiPS)." (PMID 29439516, 2018).
Rhabdoid Meningioma (1 paper, 2022). A WHO grade III meningioma characterized by the predominant presence of rhabdoid cells forming sheets. "In this regard, SMO, AKT, and PIK3CA mutations are typical of anterior skull base meningiomas, whereas KLF4 mutations are specific for secretory histology, and BAP1 alterations are common in progressive rhabdoid meningiomas." (PMID 35565385, 2022).
sarcoidosis (1 paper, 2025). Sarcoidosis is a multisystemic disorder of unknown cause characterized by the formation of immune granulomas in involved organs. "Among the twelve common DEGs, SALL4, WNT10A, RASAL1, CAMK2B were significantly upregulated while GADD45B, KLF4, OLR1, CSF3, WIF1, RAMP3 and AGER downregulated in both sarcoidosis and LC as compared to the controls." (PMID 40797277, 2025).
serous ovarian cancer (1 paper, 2022). "An high-grade serous ovarian cancer (HGSOC) cell line, OVCAR-3 was reprogrammed by transducing Yamanaka four factors OCT4, SOX2, KLF4 and MYC (OSKM) to establish an iOCIC model, iOVCAR-3-OSKM." (PMID 36085021, 2022).
signet ring cell carcinoma (1 paper, 2016). A usually aggressive, poorly differentiated invasive adenocarcinoma characterized by the presence of malignant glandular cells in which the nucleus is pressed to one side by the presence of intracytoplasmic mucus. "It is possible that KLF4 and MUC2 could be used as diagnostic markers in signet ring cell carcinoma." (PMID 27277677, 2016).
silicosis (1 paper, 2025). Silicosis is a respiratory disease caused by breathing in (inhaling) silica dust. "In silicosis, vitamin D facilitates macrophage polarization toward the M2 phenotype via KLF4, thereby reducing inflammation in damaged tissues." (PMID 40640934, 2025).
skin inflammation (1 paper, 2026). "KLF4 and NF-κB collaborate to upregulate IL-36γ promoter activity, thereby inducing neutrophil recruitment via IL-8 and worsening skin inflammation." (PMID 41570298, 2026).
skull base tumors (1 paper, 2025). "Genotype (p = 0.004) and WHO grade (p = 0.002) were significantly associated with tumor location: NF2 alterations predominated in convexity and spine, while TRAKLS mutations (TRAF7, AKT1, KLF4, SMO) were enriched in lower-grade skull base tumors." (PMID 40951339, 2025).
Splenomegaly (1 paper, 2020). Abnormal increased size of the spleen. "Consequently, KLF4 re-expression resulted in a reduction in splenomegaly compared with that in mock gene-bearing mice." (PMID 32944247, 2020).
systemic lupus erythematosus (1 paper, 2023). An autoimmune multi-organ disease typically associated with vasculopathy and autoantibody production. "We previously reported that downregulation of two miRNAs, miR-128 and miR-148a, additively alters their target KLF4 via extensive overlapping of target sites, leading to enhancement of the inflammatory responses in plasmacytoid dendritic cells in the systemic lupus erythematosus (SLE) mouse model." (PMID 36672241, 2023).
thymic atrophy (1 paper, 2023). "The striking pregnancy-induced thymic atrophy in Klf4-deficient mice had a long-lasting impact on mature cTECs and thymocyte development." (PMID 37180153, 2023).